TLR4 (toll like receptor 4)
Diseases named in the same sentence as TLR4 in open-access papers (continued):
Sharing a sentence is not in itself a finding about the gene and the disease.
Obesity (continued). "Saturated fatty acids, which are elevated in obesity, are able to bind and activate toll-like receptor 4 (TLR4) and inhibition of TLR4 or neuronal deletion of the TLR adaptor molecule MyD88 protects from HFD-induced leptin resistance and obesity." (PMID 28270795, 2017). "Either inhibition of TLR4 expression or blockade of TLR4 signaling pathway in the hypothalamus can improve peripheral insulin resistance, and restore glucose homeostasis during the course of diet-induced obesity." (PMID 28785099, 2017). "The obesity related metabolic disorders and inflammation were ameliorated after down-regulation of Tlr4 mRNA expression, excluding the fasting glucose and triglyceride." (PMID 28785099, 2017). "We also analyzed mRNA expression of fibronectin and Tenacin C1, which are reported to serve as endogenous ligands for TLR4 to promote inflammation in HFD-induced obesity and in arthritis model." (PMID 28898202, 2017). "In the current study, analysis of epidymymal fat pads of C57/Bl6 male mice, we found that, in contrast to data from diet-induced obesity models, adipose tissue from aged mice have normal Fet A and TLR4 expression." (PMID 28898202, 2017). "In obesity, LPS is derived from excess nutrients, such as saturated/free fatty acids, and gut endotoxins to activate TLR4 and perhaps other TLRs, resulting in a significant inflammatory reaction and adipocyte dysfunction." (PMID 28182687, 2017). "The involvement of Fet A-mediated activation of TLR4 pathway in adipose tissue inflammation in diet-induced obesity is well explored." (PMID 28898202, 2017). "Collectively, these results suggest that TLR4 signaling-mediated hypothalamic inflammation play a crucial role in obesity-related peripheral insulin resistance." (PMID 28785099, 2017). "Studies in diet-induced obesity have characterized the role of Fetuin A (Fet A) in Free Fatty Acids (FFA)-mediated TLR4 activation and adipose tissue inflammation." (PMID 28898202, 2017). "The obesity related abnormal gluconeogenesis was significantly ameliorated by down-regulation of Tlr4 mRNA expression (P < 0.05)." (PMID 28785099, 2017). "Although TLR4 signaling pathway has been studied in chondrocytes and cartilage, the role in obesity-related OA is not fully understood." (PMID 28250578, 2017). "The obesity-related inflammation in the livers from obese rats was ameliorated after down-regulation of Tlr4 mRNA expression." (PMID 28785099, 2017). "Our data suggest that down-regulation of TLR4 mRNA expression in the hypothalamic ARC is an effective way to improve obesity related metabolic disorders." (PMID 28785099, 2017). "The present study examined the modulatory function of TLR4 in visceral pain in a model of diet-induced obesity." (PMID 27159520, 2016). "Recent studies have shown a role for FBXW7 in attenuating TLR4 expression and, thereby, macrophage response to lipopolysaccharide and other ligands such as palmitic acid which is elevated in obesity and insulin resistance." (PMID 27812198, 2016). "TLR4 signaling in immune cells plays a key role in the development of obesity- and endotoxin-mediated adipose tissue fibrosis." (PMID 26975571, 2016). "In conclusion, the results from this experiment help to elucidate the mechanisms behind TLR4/c-Src/EGFR signaling in the pathogenesis of obesity-related renal injury." (PMID 27014908, 2016). "Summarizing our main results, we demonstrated that the blood monocyte TLR4 level positively correlated either with NAFLD or obesity; prediabetic, obese patients with NAFLD and MetS were characterized by the highest level of this receptor." (PMID 26930651, 2016). "These lipid and glucose metabolic changes seemed to be highly dependent on TLR4 expression since TLR4−/− mice were protected from obesity and its complications." (PMID 26921251, 2016).
Obesity (continued). "Toll-like receptor 4- (TLR4-) mediated NF-κB activation in obesity severely impairs cold-induced type 2 immune responses, downregulates PPARγ and PPARα expression, and markedly reduces beige fat development." (PMID 28042289, 2016). "This study has confirmed the detrimental effect of EGFR activation in the pathogenesis of obesity-induced cardiac inflammatory injuries in experimental mice, and has demonstrated the TLR4/c-Src-mediated mechanisms for PA-induced EGFR activation." (PMID 27087279, 2016). "The link between diet-induced obesity and TLR4 was also described in studies demonstrating that TLR4 knockout mice are resistant to develop a diet-induced phenotype when fed high-fat diet for several month." (PMID 27159520, 2016). "There is growing evidence from studies using murine models of obesity that activation of the proinflammatory TLR4/NFκB pathway constitutes one mechanism that links inflammation and metabolic disorders." (PMID 25873766, 2015). "Many studies demonstrated that decreased TLR4 expression protects from obesity development, adipose tissue inflammation and insulin resistance." (PMID 26635627, 2015). "Lauric acid is a saturated fatty acid released by adipocytes, especially upon obesity-induced lipolysis, and a ligand of TLR4, highly expressed by macrophages; the possible macrophage chemotactic capacity of this fatty acid had not been analyzed either." (PMID 25599228, 2015). "Studies suggest that obesity TLR4 signaling essentially depends on MyD88 expression and up-regulated NF-κB activity, with IL-6 and TNF-α pro-inflammatory cytokines increased expression." (PMID 26635627, 2015). "In rodents and humans with obesity and insulin resistance, elevated expression and downstream signaling of TLR4 has been demonstrated in insulin-target tissues (muscle, liver and adipose tissue) and immune cells (monocytes and macrophages)." (PMID 26196892, 2015). "The similar influence of obesity was observed when TLR4 expression on blood monocytes was measured by flow cytometry." (PMID 26629827, 2015). "TLR4 activation, which occurs in obesity, can be activated by gut microbial patterns, such as LPS, to promote inflammatory mediators production." (PMID 26635627, 2015). "Strong evidence links TLR4-mediated inflammation in conditions such as obesity, insulin-resistance and diabetes." (PMID 26435700, 2015). "A recent study also identified TLR4 signaling pathway as a direct key mediator of vascular inflammation and impairment of endothelial insulin signaling in the setting of obesity." (PMID 25873766, 2015). "Chronic low-dose endotoxin application was consequently found to cause obesity and insulin resistance in rodent models while knockout of TLR4 prevented diet-induced obesity, glucose intolerance, and atherosclerosis." (PMID 26635805, 2015). "First, mice deficient in the two TLRs that use TRIF—TLR4 and TLR3 —are protected from obesity-induced VAT inflammation and insulin resistance." (PMID 26317499, 2015). "There are some similarities with cardiometabolic complications due to obesity, the latter resulting from inflammation involving TLR4 signaling." (PMID 25873766, 2015). "The chronic nature of obesity produces a tonic low-grade activation of TLR4 that impairs insulin action over time." (PMID 26196892, 2015). "Saturated fatty acids produce an inflammatory response predominantly through the activation of TLR4 signaling in hypothalamus: implications for the pathogenesis of obesity." (PMID 25184806, 2014). "Activation of TLR4 in adipose tissue has contributed to obesity-induced inflammation and insulin resistance." (PMID 25546437, 2014). "Activation of inflammatory pathways through TLR4 signaling represents a key step in the development of insulin resistance in obesity." (PMID 25546437, 2014). "The activation of TLR4 by FFAs and subsequent upregulation of intracellular inflammatory pathways establish a link between the innate immunity and diet induced obesity and insulin resistance." (PMID 24594974, 2014).
Obesity (continued). "Subsequently, we examined the effect of quercetin on inflammatory receptors such as TNF receptor superfamily member 9 (4-1BB) and toll-like receptor 4 (TLR4), which are known to promote obesity-induced inflammatory responses in skeletal muscle." (PMID 25614714, 2014). "Free fatty acids, whose concentration is high in obesity, have been shown to activate TLR4 and to promote cytokine production and inflammation." (PMID 24740015, 2014). "Activation of TLR4 signaling by increased circulating FFAs during obesity-related diseases has been suggested to be a key contributor to this up-regulation of TLR4 signaling." (PMID 25101057, 2014). "TLR4 signaling is a key link between exogenous and endogenous innate immune antigens and downstream metabolic complications of chronic inflammation in obesity, insulin resistance and atherosclerosis." (PMID 23497455, 2013). "Both TLR-2 and TLR-4 expression are increased in adipose tissue in patients with obesity and type 2 diabetes mellitus." (PMID 23800102, 2013). "Of interest, RP105 KO and MD-1 KO mice have less HFD-induced obesity, adipose tissue inflammation, hepatic steatosis and insulin resistance compared to WT and TLR4 KO mice." (PMID 24064574, 2013). "The activation of the TLR4/NF-κB signaling pathway can induce and aggravate insulin resistance, which leads to obesity and related metabolic disorders." (PMID 23251812, 2012). "The objective of the present study was to elucidate the mechanism for a link between HFD and obesity, particularly the effects of endotoxin-induced inflammation via TLR4 signaling pathway in response to a HFD." (PMID 23091640, 2012). "HFD induces inflammation by increasing endotoxin levels in the intestinal lumen as well as in the plasma by altering the gut microbiota composition and increasing its intestinal permeability through the induction of TLR4, thereby accelerating obesity." (PMID 23091640, 2012). "Recently it has been proposed that during obesity, metabolic endotoxemia contributes to the development of inflammation and metabolic disorders through the activation of TLR4 in metabolic tissues." (PMID 23316186, 2012). "The extent of the obesity-induced up-regulation of TLR2/TLR4 genes and related proinflammatory cytokines cascades related to the BMI values." (PMID 23191980, 2012). "CNS deletion of Toll-like receptor 4(TLR4) adaptor MyD88 protected mice from high fat diet-mediated obesity." (PMID 22035457, 2011). "Adipocytes express both TLR2 and TLR4 and the expression of these receptors is upregulated in obesity." (PMID 21356117, 2011). "Consistent with this notion are reports indicating that in TLR4-knockout mice, diet-induced obesity and inflammation is abrogated." (PMID 20508722, 2010). "Saturated FFA are potent activators of the Toll-like receptor-4 (TLR4) and recent evidence suggests that inflammatory processes induced by obesity and a high-fat diet cause systemic insulin resistance via a mechanism involving this receptor." (PMID 20706688, 2010). "SFA activation of TLR4 is an attractive link between obesity, insulin resistance, and inflammation, as cellular exposure to SFA greatly increases in the obese state." (PMID 20814545, 2010). "FFA and other molecules produced by hypoxic conditions during obesity activate these receptors, particularly TLR4." (PMID 20671929, 2010). "Toll-like-receptor 4 (TLR) is discussed to provide a molecular link between obesity, inflammation and insulin resistance." (PMID 21125016, 2010). "Several studies to date have shown that disruption of the TLR4 gene in mice confers protection from obesity-induced inflammation and insulin resistance." (PMID 20814545, 2010). "The concentrations of these fatty acids, particularly saturated free fatty acids, are reported to be elevated in obesity and directly induce inflammatory responses in macrophages via toll-like receptor 4 (TLR4), the lipopolysaccharide receptor." (PMID 20508825, 2010).
Obesity (continued). "It was recently demonstrated that TLR4 activation via dietary lipids triggers inflammatory pathway and alters insulin responsiveness in the fat tissue during obesity." (PMID 20339530, 2010). "Extensive literature suggests that high-fat diet-augmented postprandial endotoxemia is a possible mode by which dietary SFAs induce inflammation through TLR4 in diet-induced obesity (DIO) models." (PMID 20814545, 2010). "Additionally, TLR4 activation provoked insulin resistance in adipocytes, suggesting that activation of TLR4 in adipocytes might be implicated in the onset of insulin resistance in obesity and type 2 diabetes." (PMID 18298826, 2008). "The association between high-fat diets, increased circulating LPS levels, and chronic low-grade inflammation is well-established, with elevated LPS levels contributing to the development of obesity and insulin resistance through TLR4-mediated signaling pathways." (PMID 40530326, 2025). "Studies have found that TLR4 activation and subsequent inflammatory responses are key regulators to suppress adaptive thermogenesis, Obesity-mediated TLR4 activation represses adaptive thermogenesis through endoplasmic reticulum (ER) stress-mediated mitochondrial dysfunction." (PMID 40270019, 2025). "Although the impact of obesity on central and hormonal regulation of GI motility has been well characterized in colonic tissues, only a few studies have examined the effects of HFD and TLR4 deficiency on ENS activity of the small intestine." (PMID 41226745, 2025). "In Toll-Like Receptor 4 (TLR4) mice, HFD-induced obesity activates phosphorylated Akt (pAkt) in the liver, with TLR4 signaling—via NF-κB activation—leading to palmitic acid-induced vascular inflammation and insulin resistance, disrupting endothelial NO signaling." (PMID 40564033, 2025). "In obesity, adipose tissue macrophages (ATMs) shift from an anti-inflammatory M2 to a pro-inflammatory M1 phenotype, largely in response to microbial-derived LPS, via TLR4-mediated signaling." (PMID 40507152, 2025). "The proliferation of Erysipelatoclostridium, particularly E. ramosum, may exacerbate high-fat diet–induced obesity and metabolic disturbances by disrupting the gut barrier and activating inflammatory pathways such as TLR4." (PMID 41458627, 2025). "E. ramosum is an opportunistic pathogen involved in clinical infections and bacteraemia and may promote obesity through Toll-like receptor (TLR)-4 signalling-mediated inflammatory pathways." (PMID 40863141, 2025). "In an obesity model, anthocyanins were able to reduce body mass and adipose tissue mass, positively impacting the secretion of the adipokines leptin and resistin, corroborating the improvement of inflammation by modulating the TLR4/AMPK pathways." (PMID 40195898, 2025). "Therefore, these compounds provided the material basis for ECT‐mediated regulation of obesity through the TLR4/MyD88/NF‐κB signaling pathway." (PMID 40772014, 2025). "Additionally, it can modulate the gut microbiota, suppress the TLR4/Myd88/NF-κB inflammatory pathway, and effectively combat obesity and hyperlipidemia in mice fed a high-fat diet." (PMID 41584839, 2025). "The interaction of adipocytes and macrophages in the TLR4/NF-κB pathway may be a point of interest in alleviating obesity-induced inflammation in the heart and other organs." (PMID 39198360, 2025). "Furthermore, a dual relationship can exist with some factors (e.g. obesity; TLR4 within the TME) initially offering protection to cancer development de novo but contributing to progression once malignancy is established." (PMID 39840030, 2024). "In addition, n-6 PUFAs exacerbated obesity-related osteoarthritis, whereas n-3 PUFAs were protective against the disease by regulating the TLR4/NF-κB and NOD-like receptor protein 3 (NLRP3)/caspase-1/gasdermin D pathways." (PMID 39339730, 2024).
Obesity (continued). "The expression of TLR4 and the inflammatory response to lipopolysaccharide (LPS) was found to be increased in classical monocytes of people with obesity, and the expression of chemokine receptors and the migratory capacity of monocytes was enhanced in people with obesity." (PMID 39050851, 2024). "TLR-4 may also play the role of a “sensor” for endogenous lipids, contributing to the development of obesity-related disorders." (PMID 38674875, 2024). "This regulatory effect subsequently inhibits the TLR4/NF-κB signaling pathway involved in obesity." (PMID 38999906, 2024). "Elevated fetuin-A levels have been associated with the development of a variety of liver-related metabolic issues, including IR, adipocyte inflammation, hepatocyte fibrosis, dyslipidemia, progressive macrophage infiltration, and increased toll-like receptor-4 (TLR4) expression resulting in obesity." (PMID 39026172, 2024). "The study found that lowering TLR4 levels may improve obesity and insulin resistance in patients with type 2 diabetes, and targeted inhibition of TLR4 may be a potential target for the treatment of type 2 diabetes and its chronic complications." (PMID 38645437, 2024). "Gut-derived lipopolysaccharide (LPS), a TLR4 agonist, is elevated in obesity." (PMID 39195211, 2024). "An upregulation of TLR4 (P < 0.05), CD68 (P < 0.05), SPP1 (P < 0.05) and CCL2 (P < 0.05) together with a downregulation (P < 0.05) of ADIPOQ levels in the jejunum from patients with obesity-associated T2D were found." (PMID 38315242, 2024). "Although TLR4 plays an important role in obesity and metabolic dysfunction, it remains unclear about the specific role of TLR4 in POMC neurons." (PMID 37028769, 2023). "A suggested mechanism by which TSP1 regulates the macrophage activity and the production of inflammatory cytokines is via activating the Toll-like receptor 4 (TLR4) signaling pathway, which is considered as a main trigger of the obesity-induced inflammatory response." (PMID 37964189, 2023). "TLR-4 activation further stimulates the IKB kinase/nuclear factor kB (NF-kB) pathway, causing the production of proinflammatory cytokines, such as IL-6, IL-8, TNF, and IL1 (Hypothalamic Inflammation and Obesity: A Mechanistic Review)." (PMID 37764744, 2023). "Visfatin/NAMPT exists in two forms: intracellular NAMPT (iNAMPT) that catalyzes NAD+ biosynthesis and modulates insulin sensitivity and lipid metabolism and extracellular eNAMPT/visfatin, an inflammatory cytokine that activates TLR4/NF-κB signaling in obesity and NAFLD." (PMID 36834782, 2023). "No significant influence of TLR4 rs1928295 polymorphism on obesity-related indexes was found in female children under the interaction of dietary patterns." (PMID 37571378, 2023). "This theory was followed by a series of studies on mice and cell cultures indicating that the downregulation of Toll-like receptor 2 (TLR2) and Toll-like receptor 4 (TLR4) in diet-induced obesity improves adipocyte differentiation and insulin sensitivity in mice." (PMID 37446161, 2023). "This may explain why the interaction between the AFDP and TLR4 rs1928295 in male children in this study led to the increase in obesity indicators." (PMID 37571378, 2023). "The activation of TLR4 signal in hypothalamus can trigger hypothalamic inflammatory response and result in resistance to anorexia signal, which plays a key role in the occurrence of obesity." (PMID 37028769, 2023). "The lack of TLR4 signaling ameliorated the insulin and glucose signaling abnormalities associated with obesity." (PMID 36674680, 2023). "As a cell transmembrane receptor in the innate immune system, its mediated inflammatory signaling pathway is considered to be one of the main triggers of obesity-induced inflammatory response, and TLR4 activity plays a prominent role in the occurrence of obesity-related inflammation." (PMID 37571378, 2023).